CXCL13 (C-X-C motif chemokine ligand 13)
Diseases named in the same sentence as CXCL13 in open-access papers (continued):
Sharing a sentence is not in itself a finding about the gene and the disease.
tumor (continued). "Our experiments, both in vitro and in vivo, demonstrated that this novel design increases CAR-T cell migration to CXCL13-positive tumor tissues and enhances the ensuing killing of target cells." (PMID 34553036, 2021). "In most cancer types, the CXCL13/CXCR5 axis mediates pro-neoplastic immune reactions by recruiting suppressive immune cells into tumor tissues." (PMID 34947813, 2021). "As such, the overexpression of CXCL13 in tumor cells provides a potential mechanism for the sustained clinical activity seen in responders." (PMID 34795254, 2021). "In this study, we observed increased infiltrations of CD4+, CD8+ T lymphocytes, and CD11b+CD11c+ DC in a CXCL13-expressing 4T1 tumor microenvironment." (PMID 35693216, 2021). "Chemotactic CAR-T cells show superior trafficking toward tumor sites and enhanced cytotoxicity: a proof of concept study of CXCR5-EGFR-CAR-T for the CXCL13+ NSCLC tumor." (PMID 34553036, 2021). "Surface markers (PD1 and ICOS) had similar expression panels in tumors and spleens, and significantly different expression levels of functional effectors (CXCL13 and IL-21) reflected the diverse status of tumor-infiltrating Tfh cells exposed to tumor antigens." (PMID 34359579, 2021). "In contrast, numerous genes, including CXCL13, were upregulated in the tumor cells of responders post-treatment compared to pretreatment (see CXCL13 in bold)." (PMID 34795254, 2021). "In vivo experiments further proved that CXCL13 secreted by M2 macrophages can promote tumor proliferation." (PMID 34922542, 2021). "Taken together, Tfh cells played anti-tumor role via CXCL13-dependent recruitment of CD8+ T cells and B cells and IL-21-dependent B cell maturation." (PMID 34359579, 2021). "CSx-resolved tumor cell-specific CXCL13 expression was significantly increased in responders post-treatment compared with other patient groups on a per tissue microarray spot basis." (PMID 34795254, 2021). "In this study, our analysis results showed that the mRNA levels of CXCL13 in HNSCC tissues were significantly upregulated when compared with non-tumor tissue." (PMID 33489879, 2020). "Several of these markers including MS4A1, CXCR5, and CXCL13 are also suppressed across all stages (Stages 1–4) with respect to normal, further emphasizing their role in sustaining tumor behavior within LSCC." (PMID 32293332, 2020). "CXCL11 and CXCL13 are associated with CD8+ T cell and B cell infiltration, which act as a protective factor inhibiting tumor." (PMID 32208363, 2020). "In our study, our results also revealed that compared with normal lung epithelial cells, CCL5 and CXCL13 had higher expressions in tumor cells." (PMID 32549766, 2020). "Similar to B cells, CXCL13 has been identified as possessing a dualistic impact on tumor progression." (PMID 33193299, 2020). "Both B cells and CXCL13 possess dualistic impacts on tumor progression and tumor immunity which is furthered detail in this review." (PMID 33193299, 2020). "Paradoxically, CXCL13 has been shown to drive several pro-growth and invasive signaling pathways across multiple tumor types, while also, correlating with improved survival and immune cell tumor localization in other tumor types." (PMID 33193299, 2020). "CXCL13 is a member of the chemokine family and is an important component of the tumor microenvironment." (PMID 33110086, 2020). "In humans, CXCL13 has been shown to increase B cell tumor infiltration and correlate with prolonged survival in multiple tumor types." (PMID 33193299, 2020). "Instead, new tools that enable real-time tracking of CXCL13 expression during tumor progression are necessary to more accurately address this inquiry." (PMID 33193299, 2020). "Further research needs to perform to investigate the expressions of CCL5 and CXCL13 in tumor and T cells." (PMID 32549766, 2020).
tumor (continued). "Treatment with CEA-TCB triggered secretion of pro-inflammatory cytokines (IFNγ, TNFα, IL-2) and several chemotactic molecules (CXCL9, CXCL10, CXCL11, CXCL13) indicating the generation of a highly inflamed tumor microenvironment." (PMID 33330050, 2020). "In summary, we produced a list of tumor microenvironment-related genes and identified CXCL13 expression level correlated with poor prognosis and increased TIICs of ccRCC." (PMID 32669964, 2020). "For example, CXCL13 interacts with the chemokine receptor CXCR5 which is present on B cells and some tumor cells and has been implicated as key modulators of both tumor progression and antitumor immunity." (PMID 33193299, 2020). "GESA analysis enriched immune response and cell adhesion pathway, indicating that CXCL13 had potential role in tumor migration." (PMID 32669964, 2020). "In this review we will delve into the literature of B cells and CXCL13 and attempt to provide the most updated analysis of their roles in tumor immunity." (PMID 33193299, 2020). "Studies have shown that CXCL13 can drive tumor growth and invasion through PI3K/AKT signaling or contribute to an enhanced antitumor immune response via increased tumor immune localization." (PMID 33193299, 2020). "Tumor-secreted cytokines (CXCL13 and IL-7) induce the formation of lymphoid tissue inducer (LTi) cells, which interact with local stromal cells via Lymphotoxin-α1β2." (PMID 32974337, 2020). "In conclusion, we obtained a list of tumor microenvironment-related genes and identified CXCL13 as an immune response biomarker in patients with ccRCC, GSEA analysis, wound healing and transwell assays showed CXCL13 played a role in tumor migration." (PMID 32669964, 2020). "Expression of IFNG, CD30, CXCL13, and PRF1 was associated with increased level of immune infiltrates (CD8+ T cells, dendritic cells, and neutrophils) within the tumor." (PMID 31998644, 2019). "Current evidence also indicates that the CXCL13:CXCR5 axis orchestrates cell-cell interactions that regulate lymphocyte infiltration within the tumor microenvironment, thereby determining responsiveness to cytotoxic and immune-targeted therapies." (PMID 31354634, 2019). "A screening analysis of abnormally high inflammatory factors in NSCLC patients from this region revealed that 90% of the tumor tissues have elevated CXCL13 levels." (PMID 31354634, 2019). "Carcinogens have been found to induce CXCL13 production, and production of this chemokine within the tumor milieu has been shown to impact the proliferation, migration, and invasive properties of cancer cells." (PMID 31354634, 2019). "Infiltration of TFH cells is important for tertiary lymphoid structure formation and to generate germinal center B cell responses at the tumor site by the production of CXCL13." (PMID 31354634, 2019). "After castration, there was elevated expression of CXCL13 in myofibroblasts within the tumor remnants." (PMID 31354634, 2019). "Administration of antibody-guided LIGHT activated lymphotoxin-beta receptor signaling which, in turn, facilitated production of chemokines CCL21 and CXCL13 that recruited T cells into the tumor." (PMID 30873179, 2019). "Pro-tumor: CCL21-mediated recruitment of ILC3 triggers CXCL13 secretion by TME stromal cells thereby enhancing tumor cell motility and promoting lymph node metastasis." (PMID 32117199, 2019). "Tumor CXCL13 content also had an independent influence on DDFS in a multivariable analysis adjusted for age at the time of study entry, tumor size, axillary nodal status, and histological grade of differentiation (HR 0.39, 95% CI 0.19–0.79; P = 0.009)." (PMID 29482642, 2018). "Despite this, high cancer CXCL13 expression was associated with favorable DDFS in univariable survival analysis, and tumor CXCL13 expression had an independent influence on survival also in a multivariable model." (PMID 29482642, 2018).
tumor (continued). "We observed that the mRNA expression of CCL5 and CCR5 as well as LTβR-related chemokines, such as CCL21, CCL19 and CXCL13 were substantially enhanced in the tumor tissue of EL4-Axl-bearing mice compared with mock control." (PMID 28423548, 2017). "For example, tumor-associated macrophages (TAMs) have been shown to secrete the homeostatic chemokines, CXCL12 and CXCL13, which bind to their respective G protein-coupled receptors on malignant B cells, CXCR4 and CXCR5." (PMID 28424405, 2017). "In patients with PCNSL, CXCL13 is made primarily by the malignant B cells that form the tumor itself." (PMID 28603659, 2016). "In the tumor samples from NOD/SCID mice injected with A549-Luc-CXCL13 cells and BaP-treated Cxcr5+/+ mice, the expression of E-Cadherin was low, while the N-Cadherin and nuclear β-catenin were high." (PMID 26565418, 2015). "High CXCL13 levels and GPS were significantly associated with high tumor burden predicting poor prognosis including stages III/IV, extranasal presentation, bone marrow invasion, and presence of Epstein-Barr virus (EBV) DNA in blood." (PMID 25966773, 2015). "On the other hand, in the subgroup analysis based on tumor burden, grouping by the serum level of CXCL13 and GPS discriminated patients with poor survival outcomes among those with stage I/II disease and/or with non-detectable EBV DNA." (PMID 25966773, 2015). "We expanded these observations, and found that the expression of CXCL13 was elevated in the tumor tissues from 63/70 (90%) HPR patients and 71/131 (54.2%) CR patients compared with their normal controls." (PMID 26565418, 2015). "Using immunohistochemistry (IHC) and immunoreactivity scoring, we showed that the expression of the CXCL13 protein was significantly higher in the tumor samples than their adjacent normal controls." (PMID 26565418, 2015). "Because plasma CXCL13 levels are correlated with those in the liver in mouse models, and our data showed an elevated serum concentration of CXCL13 in HCC patients, the expression status of CXCL13 in tumor tissues was further examined." (PMID 26517519, 2015). "We found that Cxcl13 was significantly up-regulated in the tumor samples compared with their normal counterparts at both the mRNA and protein levels, which paralleled the increase in Cxcl13 serum concentrations." (PMID 26565418, 2015). "We showed that compared with the A549-Luc cells, the A549-Luc-CXCL13 cells significantly increased the tumor burden in the recipient mice." (PMID 26565418, 2015). "The expression of CXCL13 was also negative in stromal cells of the tumor tissue although normal lymphocytes adjacent tumor tissue showed positive expression of CXCL13." (PMID 25966773, 2015). "Among them, CXCL13 was the most significantly up-regulated gene, with an average of 63-fold (10.48–173.65) higher expression in the tumor samples than in the normal controls." (PMID 26565418, 2015). "This points to a pivotal and expected role for CXCL13 as one of the major organizers of an anti-tumor immune response in TLS." (PMID 24762633, 2014). "In summary, factors regulating TLS formation in epithelial tissues, such as the chemokines CCL19, CCL21 and CXCL13, and the cytokine LTαβ, most likely also contribute to an anti-tumor immune response in several carcinomas/adenocarcinomas." (PMID 24762633, 2014). "Murine CXCL13 levels in tumor ascites were generally extremely high, with an average value of nearly 200,000 pg/ml." (PMID 23936541, 2013). "Third, the fact that high levels of murine, but not human, CXCL13 are present in the serum and ascites fluid of animals with 2F7-derived tumors suggests that non-tumor mouse cells are responsible for CXCL13 production in this model." (PMID 23936541, 2013). "CXCL11 has angiostatic properties and promotes the migration of cytotoxic T lymphocytes toward tumors triggering tumor cell apoptosis while CXCL13, a B cell attracting chemokine is responsible for the development of secondary lymphoid tissue in the gut." (PMID 24312117, 2013).
tumor (continued). "We have previously reported that 2F7 cells show chemotaxis towards human CXCL13 in vitro; others have reported or inferred that murine CXCL13 can act on human CXCR5, and that human CXCL13 can induce proliferation of tumor cells in some cancers." (PMID 23936541, 2013). "Down-regulation was seen for CNTN1, CXCL13, MAOB, PAGE4, PENK, SPOCK3 in CP compared to NP as well as for HSD17B2, SALL1, TRPA1 for tumor-associated bladder stromal cells compared to normal bladder." (PMID 19737398, 2009). "Of these, chemokine CXCL13 was by far the most strongly and consistently overexpressed gene with a mean expression level in tumour samples that was 18 times higher than the one observed in autologous benign breast samples." (PMID 18781150, 2008). "Instead, CXCL13 may act through T cell‐intrinsic mechanisms or modulate other aspects of the tumor microenvironment (TME) that augment responsiveness to PD‐1 blockade." (PMID 40492496, 2025). "Moreover, CXCL13 appears to enhance the anti-tumor effects of immunochemotherapy by fostering a favorable tumor immune microenvironment." (PMID 40295492, 2025). "Tumor-infiltrating immune cells and fibroblasts in tumor tissues could secrete chemokines such as CXCL13 to produce chemotactic effects on B cell subsets." (PMID 39744696, 2025). "Notably, the prognostic benefits of CXCL13 expression in HGSOC were linked to the PD-1 blockade therapy and organization of the tumor-associated tertiary lymphoid structures." (PMID 40164596, 2025). "Moreover, low-risk patients displayed a higher proportion of CXCL13 + CD4+ and CXCL13 + CD8 + T cells, indicating a more active tumor immune microenvironment and enhanced responsiveness to immunotherapy." (PMID 40670378, 2025). "However, CXCL13 has also been reported to promote tumor metastasis by facilitating the migration of regulatory B cells and the production of IL-10." (PMID 41029827, 2025). "In support of this hypothesis, we observed that the instability of Tregs leads to the expression of CXCL13, a chemokine responsible for the recruitment of B cells and T cells to the tumor site." (PMID 40164596, 2025). "The pseudotime development of CD4+ CXCL13+ Tfh cells in the blood might indicate that the development of CD4+ CXCL13+ Tfh cells might be residential, i.e., occurs locally in the tumor compartment." (PMID 40054456, 2025). "Furthermore, the evaluation of TGCA and GEO datasets confirmed that CXCL13 expression was higher in tumor tissues than in normal tissues." (PMID 40406143, 2025). "CXCL13+ CD8+ T cells interacted with SPP1+ tumor-associated macrophages (TAMs) in non-recurrent tumors, while in recurrent tumors, they interacted with CD163+ TAMs." (PMID 40464813, 2025). "Moreover, in the healthy donor samples, it showed markedly lower expression of TIGIT, PDCD1, and CXCL13, indicating that this specific co-expression pattern is tumor-specific." (PMID 40799645, 2025). "During CRC progression, TNM‐stage‐driven remodelling of the tumour microenvironment (TME) induced progressive CD8+ T cell exhaustion marked by declining TNFRSF18 and rising CXCL13 expression in tumour‐infiltrating T cells elevation of both markers in the tumour compared with adjacent tissues." (PMID 40770837, 2025). "Taken together, these results suggest that CD4_Tfh_CXCL13 might be a potential favorable factor for tumor regression during NAIC, which needs further validation." (PMID 40295492, 2025). "Thus, we confirmed the increase in the number of CXCL9+ cells and CXCL13+ cells and their concentration within and peripheral to the tumour in all four patients following post-PD-L1-CRT." (PMID 40670667, 2025). "Notably, the cytokine C-X-C Motif Chemokine Ligand 13 (CXCL13) emerged as a key regulator, with its high expression marking an immune-active tumor microenvironment favorable to ICI efficacy." (PMID 40971094, 2025). "Immune cells that express more chemokines, including CXCL13, may attract tumor cells and more immune cells with receptors to drain LNs." (PMID 40584290, 2025).
tumor (continued). "However, in many cancer types, the CXCL13/CXCR5 axis also promotes the recruitment of immunosuppressive cells to the tumour site." (PMID 40361472, 2025). "In HPV-positive tumor cells, induction of CXCL13 in CD4+ T cells lead to increased secretion of IFN-γ, which contributes to elevated tumor-infiltrating lymphocyte (TIL) counts and improved immune cell infiltration, thereby enhancing the prognosis of HNSCC patients." (PMID 40486875, 2025). "Lactate from LDHA-overexpressing tumors may suppress CXCL13-mediated immune cell recruitment, creating a “cold” tumor microenvironment." (PMID 40260244, 2025). "Accordingly, CXCL13 has been shown to promote tumor cell proliferation." (PMID 40325003, 2025). "The dynamic changes of the cytokine CXCL13 at each stage of the tumor may affect the infiltration and function of Tfh cells." (PMID 40287532, 2025). "Importantly, increased CXCL13 expression was found in neoantigen-reactive T cells, an observation that extends across various tumor types." (PMID 40164596, 2025). "Additionally, CXCL13 can induce the expression of forkhead box P3 (Foxp3) in Tregs, which is crucial for suppressing tumor immunity." (PMID 40692663, 2025). "MP2 lysate-pulsed 1st and 2nd Gen DCs significantly reduced tumor burden compared to untreated or UTD DC-treated mice, highlighting the capacity of antigen-loaded DCs engineered to overexpress CD93, CD40L, and CXCL13 to drive robust anti-tumor immunity in the Hu-BLT model." (PMID 41295503, 2025). "However, CXCR5 expression, activated by CXCL13, can promote tumor growth via pathways such as MAPK, PI3K, and RAC1." (PMID 40636453, 2025). "Together, these findings highlight CXCL13 as a potential marker of tumor‐reactive, migratory, and functionally poised T cell subsets that may contribute to favorable clinical responses following ICB therapy." (PMID 40492496, 2025). "Although the exact mechanism by which tissue-resident memory T cells are preferentially localized within TLS remains to be fully elucidated, it has been reported that CXCL13 plays a pivotal role as the primary molecular driver behind the formation of TLS in the tumor microenvironment (TME)." (PMID 39926286, 2025). "Silencing CXCL13 was found to significantly reduce tumor growth and M2 macrophages." (PMID 41446602, 2025). "Interferon cascade activation induces the production of chemokines, such as CXCL9, which promotes the recruitment of CD8+ T cells to the tumor microenvironment and stimulates the expression of CXCL13, intensifying immune infiltration and improving the response to checkpoint inhibitor treatments." (PMID 40647506, 2025). "For example, the NeoTCR signature learned across metastatic tumour types identified high expression of the chemokines CXCL13 and CXCR6, effector genes like GZM-A/B/K, and PRF1, and inhibitory markers like TIGIT, PD1, and LAG3, as well as downregulation of stemness markers including IL7R and KLF2." (PMID 40801654, 2025). "As expected, CXCL13 CAR T cells demonstrated superior tumor control in this model." (PMID 40492496, 2025). "The findings presented demonstrated that CXCL13 might be a potential indicator for tumor features and survival in patients with CRC." (PMID 40943634, 2025). "Furthermore, activated CD8Teff cells enhance their tumor-killing capacity by secreting increased levels of CXCL13, which mediates interactions with NK cells, tumor cells, CAFs, and vascular endothelial cells." (PMID 40971094, 2025). "To further validate the hypothesis that CXCL13+ T cells are tumor‐reactive, we scored T cells for tumor‐reactive markers and found that CXCL13+ T cells exhibited significantly higher reactivity compared to CXCL13− T cells." (PMID 39739621, 2025). "The majority of signature-based approaches rely on gene set enrichment analysis of clustered tumor-reactive T cells, and thus identify genes that are upregulated in the CXCL13 expressing cluster that we have previously shown to contain tumor-reactive infiltrating T cells." (PMID 38454173, 2025).